GHR (growth hormone receptor)
Diseases named in the same sentence as GHR in open-access papers (continued):
Sharing a sentence is not in itself a finding about the gene and the disease.
melanoma (continued). "Knockdown of GH receptor (GHR) in melanoma cells in vitro downregulates ATP-binding cassette-containing (ABC) transporters and sensitizes them to anti-cancer drug treatments." (PMID 35865483, 2022). "To assess the effects of GH responsivity in determining survival among melanoma patients with high and low GHR expression, we compared survival between melanoma patients within the top and bottom quartiles for GHR expression level." (PMID 33291663, 2020). "We believe that this study strengthens the foundations of GH-driven drug resistance and warrants future studies in combining GHR antagonism with chemotherapy in treating melanoma." (PMID 33291663, 2020). "Growth hormone (GH) and the GH receptor (GHR) are expressed in a wide range of malignant tumors including melanoma." (PMID 33291663, 2020). "Previously, we had reported that not only do melanoma cells overexpress GHR but also that targeting GHR in human melanoma cells attenuates tumor progression, EMT induction, drug efflux and more importantly, sensitizes these cells to chemotherapy in vitro." (PMID 33291663, 2020). "We previously showed that in human melanoma cells in vitro exogenously added GH upregulates markers of EMT while attenuating GHR expression decreases the EMT induction." (PMID 33291663, 2020). "A previous study implicates the GH/GHR axis in inducing chemoresistance in human melanoma by JAK2/STAT5 activation." (PMID 32069380, 2020). "GHR expression is elevated in a wide range of cancers, especially in the case of melanoma, implicating the potential involvement of GH in this process." (PMID 33291663, 2020). "Increased GH responsiveness was identified by immunohistochemical studies targeting GHR on melanoma patient-derived paraffin samples." (PMID 31547367, 2019). "Previously, we and others have described the spectrum of intracellular signaling cascades activated by GH binding to its cognate GHR dimer in human melanoma as well as in other human cancers." (PMID 31547367, 2019). "It was previously shown that GH action in GHR+ human melanoma cells upregulates while GHR knockdown suppresses the ABC-transporter system, especially ABCB1, ABCB5, ABCB8, ABCC1, ABCC2, ABCG1, and ABCG2 differentially in a drug-dependent manner." (PMID 31547367, 2019). "In order to determine if our observations result in an upregulated MITF activity, we chose to assay the tyrosinase activity as well as the melanin production rate in GH treated or GHR-blocked melanoma cells, in presence of multiple classes of anticancer drugs." (PMID 31547367, 2019). "GH and GHR are abundantly expressed in human melanoma cells, and treatment with GH resulted in decreased E cadherin and increased N cadherin, while GHR knockdown reversed the effect." (PMID 31939481, 2019). "We further queried the changes in protein level expression of MITF and a few of its target genes in these melanoma cells, following drug treatment, GH treatment, as well as GHR blockade." (PMID 31547367, 2019). "Appropriately designed in vivo and clinical studies will be invaluable and essential to bring the approach of combined GHR antagonism to overcome tumoral resistance in existing melanoma therapies from bench to bedside." (PMID 31547367, 2019). "In GHR-expressing (GHR+) cancers of breast, pancreas, colon, liver, endometrium, as well as melanoma, GH induces the process of epithelial-to-mesenchymal transition, which is a critical step in therapy evasion and invasive metastasis in tumors." (PMID 31547367, 2019). "Incidentally, melanoma cells were also found to have the highest level of growth hormone receptor (GHR) expression among the 60 different cancer cell lines in the NCI-60 panel." (PMID 31547367, 2019). "We observed readily detectable levels of hGH RNA and protein and its cognate GHR on human melanoma cells." (PMID 28223541, 2017).
melanoma (continued). "Our RT-qPCR and western blot analysis revealed that critical oncogenic signaling networks in the melanoma cell are GH-dependent and were significantly suppressed when the GHR was targeted and reduced." (PMID 28223541, 2017). "Endocrine or paracrine as well as autocrine GH binds to abundantly expressed GHR on human melanoma and activates the JAK2 as well as SRC kinases." (PMID 28223541, 2017). "Here, using human malignant melanoma cells, we examined the effects of GH excess or siRNA mediated GHR knock-down (GHRKD) on tumor proliferation, migration and invasion." (PMID 28223541, 2017). "Although none of the published reports phenotype the GHR, we have very recently been able to evaluate GHR expression in B16F10 mouse melanoma cells and found a high expression of GHR in these cells." (PMID 28223541, 2017). "To assess the effects of GHRKD on the activation states of GH regulated shared oncogenic signaling pathways, we treated scr- or GHR-siRNA transfected human melanoma cells, at 60 hr." (PMID 28223541, 2017). "Along with several reports of elevated GHR RNA and proteins in human melanoma biopsies, the melanoma cell cycle was also considered to be under an orchestrated regulation of endogenous GH, prolactin (PRL) and adrenocorticotropic hormone (ACTH)." (PMID 28223541, 2017). "The four human melanoma cells selected for this study have been reported to express GHR and are responsive to exogenous hGH treatment." (PMID 28223541, 2017). "Using GHRKD, we demonstrate that targeting GHR can be a validated point of intervention in melanoma therapeutics and deserves prompt attention in the present context of continual occurrence of chemotherapy resistance." (PMID 28223541, 2017). "Our RT-qPCR analysis of RNA confirmed high levels of GHR RNA in all four melanoma cells which were reduced by almost 90% following GHR-KD." (PMID 28223541, 2017). "Recent reports have confirmed highest levels of growth hormone (GH) receptor (GHR) transcripts in melanoma, one of the most aggressive forms of human cancer." (PMID 28223541, 2017). "Increased lung nodule formation in DJ-1 KO mice following intravenous injection of melanoma cells was inhibited by GHR knockdown in B16F10 cells." (PMID 27825319, 2016). "Moreover, our previous research has shown elevated levels of GH and GHR RNA in the SK-MEL-28 melanoma cells following treatment with chemotherapies, including doxorubicin." (PMID 39123364, 2024). "Therefore, a GHR antagonist is a candidate negative regulator of melanoma cell growth and therapeutic response." (PMID 37442239, 2023). "Previously, we had identified the highest GHR expression in human melanoma cells in the NCI-60 cell lines and also demonstrated that GH upregulates resistance to doxorubicin, cisplatin, paclitaxel, and vemurafenib by increasing the expression of ABCB, ABCC, and ABCG groups of ABC transporters." (PMID 35865483, 2022). "Based on our series of in vitro studies with human and mouse melanoma cells and in vivo study with syngeneic melanoma mouse models of GH excess, here, we hypothesized that a GHR antagonist (GHRA) might successfully suppress melanoma tumor growth in vivo." (PMID 35865483, 2022). "To corroborate whether GHR antagonism can sensitize melanoma to chemotherapy, as indicated by our earlier in vitro studies, we intradermally inoculated GHA and WT mice with Fluc-B16-F10 cells on the flank." (PMID 35865483, 2022). "We have also shown that siRNA-mediated GHR knockdown in human melanoma cells attenuated tumor progression, epithelial-to-mesenchymal transition (EMT) and sensitized these cells to chemotherapy by attenuating expression of ATP-binding cassette (ABC) multidrug efflux pumps." (PMID 33291663, 2020). "Additionally, enhanced metastasis of mouse melanoma cells to the lungs in response to locally elevated GH levels in DJ-1 knockout mice was recently reported and confirms a role of GHR in melanoma metastases." (PMID 33291663, 2020).
melanoma (continued). "Therefore, we closely monitored the production of GH and GHR RNA production in human melanoma cells following addition of anticancer drugs, across four different time points." (PMID 31547367, 2019). "We aimed to examine whether there is a connection between lung GH expression and lung metastasis of GHR-expressing melanoma cells." (PMID 27825319, 2016). "Moreover, several studies have shown that melanoma cell lines express high levels of growth hormone receptor and respond to GH treatment." (PMID 27825319, 2016). "In this study, we found that GHR down-regulation reduced lung metastasis of melanoma cells." (PMID 27825319, 2016). "In context of the improved response to chemotherapy in combination with attenuated GH action in our earlier in vitro and current in vivo studies in melanoma, we further hypothesized that other cancer types with GHR expression may also be amenable to this therapy sensitizing effects." (PMID 35865483, 2022). "Therefore, melanoma presented as an ideal cancer type to verify the hypothesis of whether a GHR antagonist can sensitize the effect of chemotherapy in a suitable mouse model." (PMID 35865483, 2022). "In fact, in silico analysis of melanoma patient cohorts from the Cancer Genome Atlas (TCGA) database also showed a higher number of deaths in male patients with high GHR (above mean GHR expression) compared to low GHR (below mean GHR expression) when segregated by tumor stage." (PMID 31547367, 2019). "Therefore, it was reasonable to hypothesize that GH putatively occupies a central regulatory role in melanoma cell physiology and the GHR can be targeted to abrogate multiple mechanisms of growth and progression of this type of cancer." (PMID 28223541, 2017). "However, it needs further examination to verify whether up-regulated expression of GHR in melanoma can increase the incidence of lung metastasis." (PMID 27825319, 2016). "Previously, we have identified the expression of the GH receptor (GHR) gene in multiple NCI-60 cell lines, with overexpression observed in melanoma." (PMID 39123364, 2024). "Therefore, in light of our series of in vitro observations in melanoma, we first hypothesized that targeting GHR in melanoma can improve the response of the tumor to anti-cancer drugs by attenuating ABC transporter expression in a pre-clinical mouse model of melanoma." (PMID 35865483, 2022). "We intradermally inoculated Fluc-B16-F10 mouse melanoma cells into GHA mice, transgenic for a GHR antagonist (GHRA), and observed a marked reduction in tumor size, mass and tumoral GH signaling." (PMID 35865483, 2022). "Human patient data for melanoma and HCC show that GHR RNA levels correlate with ABC transporter expression." (PMID 35865483, 2022). "Recently, we reported that knocking down the GHR attenuated both ABC-type multidrug efflux pump gene expression and markers of EMT in multiple human melanoma cell lines, thereby improving drug efficacy." (PMID 33291663, 2020). "Using realtime RT-qPCR, immunocytochemistry and western blotting, we evaluated RNA and protein expression levels of GH and GHR, as well as IGF-1 and IGF-1R in human and mouse melanoma cell lines." (PMID 33291663, 2020). "Further, GHR and MITF clustered together among the top 20 differentially upregulated genes between human melanoma (metastatic and primary) sample gene expression data extracted from the GSEA7553 set and ranked by high and low PGC1A expression levels." (PMID 31547367, 2019). "In agreement with recent comprehensive reports of IGF gene expressions in melanoma, we found low levels of IGF1 and very high levels (25-fold greater than GHR) of IGF1R and IGF2R expression (Figure 5a1)." (PMID 28223541, 2017). "Since GHR is expressed in melanoma cells and GH can enhance the malignant effects of B16F10 melanoma cells in vitro and lung metastasis in vivo, we then used GHR-knockdown B16F10 cells to examine the effects of lung GH in DJ-1 KO mice." (PMID 27825319, 2016).
melanoma (continued). "A query of human tumor transcriptomic data for 471 melanoma patients from The Cancer Genome Atlas (TCGA) dataset revealed a positive correlation of IGF1 and ABCC9, ABCG1, ABCB1, and ABCC4 with GHR expression, and ABCC1 with both GHR and IGF1R expression, supporting our observations." (PMID 35865483, 2022). "We show that a circulating GHRA successfully and significantly improves cisplatin (in melanoma) or sorafenib (in HCC) effects and acts as a springboard for future investigations directed at assessing treatments with approved GHR antagonists and anti-cancer drugs for GHR-expressing human cancers." (PMID 35865483, 2022). "We proceeded to evaluate the effect of the GH/IGF-1 axis in vivo in mouse syngeneic model for melanoma in C57BL/6J male and female mice transgenic for bovine GH (bGH mice) and in mice insensitive to GH action due to a dysfunctional GHR ‘knock-out’ (GHRKO mice)." (PMID 33291663, 2020). "In fact, the GHR expression on the melanoma cell lines was markedly higher than the same in non-transformed skin fibroblasts." (PMID 33291663, 2020). "Therefore, our study hints at the mechanistic rationale of combining GHR antagonism with IGF1R inhibition, as a logical treatment combination in malignant human melanoma." (PMID 28223541, 2017). "In this project we assessed the effects of siRNA mediated GHR- knock-down (GHRKD) or of excess GH on four human melanoma cell lines selected from the NCI60 panel of human cancer cells and which were also part of a recent report identifying high levels of GHR in human melanoma cells." (PMID 28223541, 2017). "GHR (but not GH) is reportedly expressed in melanoma cells; therefore, melanoma cells can respond to GH stimulation." (PMID 27825319, 2016). "For this study, we isolated exosomes from three melanoma cell lines: Malme-3M, SK-MEL-28, and SK-MEL30, each treated with the following conditions: either hGH or doxorubicin alone, hGH and doxorubicin, or a combination of hGH, doxorubicin, and pegvisomant (a GHR antagonist)." (PMID 39123364, 2024). "Therefore, we proceeded to inquire into the effects of GH and GHR in driving intrinsic drug resistance by upregulating ABC-cassette containing multidrug transporters and EMT mediators, as we recently described in human melanoma cells in vitro." (PMID 33291663, 2020). "Additionally, we queried the TCGA melanoma pan-cancer dataset and segregated the patients as GHR-high (above mean GHR FPKM value; n = 117) and GHR-low (below mean GHR FPKM value; n = 354) to look at MITF and MITF targets as well as ABC-transporter expression levels in male and female patients." (PMID 31547367, 2019).
Hepatic steatosis (19 papers, 2011 to 2025). Steatosis is a term used to denote lipid accumulation within hepatocytes. "The development of hepatic steatosis has been observed in mice with liver-specific deletion of the GH receptor (GHR), liver-specific JAK2-deficient mice, or STAT5-deficient mice." (PMID 38836220, 2024). "Elevated GHR levels are independently associated with the severity of liver steatosis and the increased prevalence of NAFLD in American adults." (PMID 39296907, 2024). "To explore the causes of hepatic steatosis resulting from GHR KO, we performed RNAseq analysis on liver tissue from GHR KO pigs." (PMID 34803486, 2021). "To explore the mechanism of AHR involvement in hepatic steatosis caused by GHR deletion, we used Co-IP experiments to verify whether there is a protein interaction between AHR and GHR." (PMID 34803486, 2021). "However, our new observations revealed an important role of GHR deficiency in promoting hepatic steatosis." (PMID 34803486, 2021). "Owing to the critical role of GHR in lipid metabolism, we focused mainly on whether GHR deficiency affects hepatic steatosis in pigs." (PMID 34803486, 2021). "However, increasing evidence is showing the association of low circulating GH levels and IGF1 levels with hepatic steatosis, and inactivating mutations in the GHR of mice resulted in hepatic steatosis due to enhanced lipogenesis and reduced TG secretion from the liver." (PMID 36296646, 2022). "GH receptor (GHR) acts as a modulator of cellular metabolism, whose loss is not lethal, but results in sub-optimal health with short stature, decreased bone mineral density, decreased muscle strength, thin skin and hair, increased adiposity, and hepatic steatosis." (PMID 35966052, 2022). "In summary, elevated GHR was found to be independently associated with an increased risk of NAFLD and the severity of liver steatosis in a sizable cohort of American adults." (PMID 39296907, 2024). "GHR in Model 3 was dramatically and positively correlated with the severity of liver steatosis according to CAP values (β = 4.97, 95% CI: 4.28, 5.66) (p < 0.001)." (PMID 39296907, 2024). "In in vivo experiments using hepatocyte-specific GHR knockdown (aHepGHRkd) mice, hepatic steatosis rapidly developed independently of systemic insulin sensitivity and lipolysis." (PMID 36699040, 2022). "Initially, we found that deletion of GHR in pigs resulted in an imbalance in glucose and lipid metabolism, culminating in marked hepatic steatosis." (PMID 34803486, 2021). "In summary, GHR KO pigs showed abnormal lipid metabolism, especially high serum levels of FFAs and hepatic steatosis, consistent with the results observed in LS patients." (PMID 34803486, 2021). "To investigate the relationship between the expression of AHR and fatty acid oxidation in hepatic steatosis induced by GHR deletion, we examined the expression of genes related to fatty acid oxidation." (PMID 34803486, 2021). "We observed high levels of free fatty acids and hepatic steatosis in GHR KO pigs, which recapitulates the abnormal lipid metabolism in LS patients." (PMID 34803486, 2021). "H&E and Oil Red O Staining revealed hepatic steatosis in these rats, along with an increase in triglyceride (TG) content in serum and liver, which is similar to mouse models of steatosis resulting from the knockout of hepatic GHR." (PMID 38836220, 2024). "Additionally, multiple linear regression analysis showed a positive correlation between GHR and the severity of liver steatosis according to CA p-values (β = 4.97, 95% CI: 4.28, 5.66)." (PMID 39296907, 2024). "A series of studies was conducted to identify the source of hepatic steatosis in GHR KO pigs." (PMID 34803486, 2021). "To explore whether the protective effects of GHR are dependent on AHR in hepatic steatosis, we carried out the rescue experiments on siGHR human hepatocytes." (PMID 34803486, 2021). "Taken together, these lines of evidence suggest that GHR deletion results in hepatic steatosis." (PMID 34803486, 2021).